CD4 (CD4 molecule)
Diseases named in the same sentence as CD4 in open-access papers (continued):
Sharing a sentence is not in itself a finding about the gene and the disease.
tumor (continued). "The high frequency of KLRG1 expression is noteworthy, as it was found in approximately 80% of cytotoxic CD4+ T cells, identifying this as a surface marker allowing isolation of this population and its enriched repertoire of tumor-shared clones." (PMID 40299576, 2025). "The study found more underdeveloped B cells, quiescent memory CD4 T cells, and M0, M1, M2 macrophages in tumor cells." (PMID 40943497, 2025). "The result showed a significant increase in the infiltration of CD8+ T cells (green) and CD4+ T cells (red) in the tumor area in the mXO10 tLNP@mIDH1 vaccine group and the Anti-PD-1 group compared to the control group." (PMID 41381536, 2025). "The treatment significantly reduced tumor growth and increased infiltration of CD11c+ DCs, CD4+ T cells, and CD8+ T cells." (PMID 41228373, 2025). "IFN-γ produced by CD4+ lymphocytes has important roles in tissue homeostasis, immune and inflammatory responses, and tumour immunosurveillance." (PMID 41148718, 2025). "Tumor-rich areas showed higher levels of follicular helper T cells, resting dendritic cells (DCs), and plasma cells but fewer resting memory CD4+ T cells and Tregs compared to immune-rich regions." (PMID 40867511, 2025). "This process promotes the differentiation of naïve CD4+ T cells into T follicular helper cells and T helper cells, thereby modulating the immunosuppressive tumor microenvironment in HCC." (PMID 41050404, 2025). "Given the differences in immune cell distribution within the tumor microenvironment, this study analyzes the density of CD4+ and CD8+ TILs in intratumoral and stromal compartments and correlates them with patient survival outcomes." (PMID 40444078, 2025). "In contrast, tsMHC‐II refers to ectopic expression of MHC‐II on malignant cells, enabling them to directly present antigens to CD4+ T cells within the tumour microenvironment." (PMID 40673641, 2025). "It was reported that the percentages of CD4+CD25+FOXP3+ Tregs were significantly increased in PDAC tumor tissues compared to control pancreatic tissues." (PMID 40427098, 2025). "The requirement of CD4+ T cells for recall response and the requirement of Bcl-6 expression in late-stage CD4+ T cells for prolonged survival prompted us to ask if M002 treatment had the potential to increase the memory feature of CD4+ T cells in the tumor." (PMID 39885128, 2025). "For example, in vivo studies have shown that transduction of tumor cells with ectopic HLA class II or CIITA increases CD4 + T cell and CD8 + T cell-mediated tumor rejection, implying that suppressing HLA class II expression is necessary for tumor progression." (PMID 39928678, 2025). "CD4+ T cells have both tumor-promoting and tumor-rejecting functions, the latter largely through providing help to CD8+ T cells." (PMID 39969434, 2025). "In tumor immunity, CD4+ Tem cells directly kill cancer cells, destroy tumor vasculature, and maintain leukocyte responses by secreting cytokines such as IFNγ and TNF." (PMID 40801655, 2025). "In conclusion, we were able to increase the response rates of MC38 tumor-bearing mice from 36% in the αPD-1 monotherapy group to 71% when early CD4-PET–guided therapy adaptation was applied." (PMID 40561008, 2025). "Later, it was confirmed that the drug inhibited tumor angiogenesis via upregulation of IFN-γ production by enhancing tumor infiltration of IFN-γ-expressing cells (CD4+, CD8+ T cells, NK cells, neutrophils and monocytes)." (PMID 40244191, 2025). "By exposing them to tumor antigens, dendritic cell (DC) therapy seeks to stimulate T-cell proliferation and encourage the activation of CD4+ and CD8+ T-cells, enabling CD8+ T-cells to penetrate the tumor microenvironment." (PMID 40227645, 2025). "Preclinical studies confirm that GITR activation increases the activity of CD8+ and CD4+ effector T cells and decreases tumour-infiltrating Tregs, particularly in HNSCC." (PMID 40994140, 2025).
tumor (continued). "Blocking immune checkpoints such as Tim-3 can enhance the anti-tumor immunity of the STING agonist ADU-S100 by regulating the release of CD4+ T cells from cDC2s." (PMID 39911388, 2025). "Regulatory T cells (Tregs), a subset of CD4+ helper T cells, play a critical role in modulating immune responses within the tumor microenvironment by producing cytokines that suppress the proliferation of effector CD8+ T cells." (PMID 40006664, 2025). "Chemotherapeutic drugs induce tumor cell death, release tumor antigens, and increase the infiltration of CD4 + and CD8 + T cells, thereby turning"cold tumors"into"hot tumors”." (PMID 40481560, 2025). "Recent studies have highlighted that A2AR expression is significantly correlated with HIF-1α, CD73, CD8, and Foxp3, and that blocking A2AR significantly reduces the number of CD4+Foxp3+ Tregs while enhancing CD8+ T cell anti-tumor responses." (PMID 40444100, 2025). "Our research further reveals that upregulation of POPDC3 is associated with increased CD4+ T cell infiltration and elevated PD-1 expression in NSCLC tissues, suggesting a possible interplay between tumor malignancy and the immune response." (PMID 39971925, 2025). "M1 macrophages inhibit the release of the immune-stimulating factor IL-12 and diminish the tumor-killing effects of NK cells and cytotoxic CD4+ T cells." (PMID 39744560, 2025). "The general principle indicates that the priming of CD4+ T cells is preferentially performed by cDC2s, which capture and present tumor‐derived antigens." (PMID 40667699, 2025). "Concurrent changes in immunoinflammatory factors within the tumor microenvironment and a significant reduction in PD-1+ Treg cells, PD-1+ CD4+ T cells, and PD-1+ CD8+ T cells in peripheral blood after TACE have also been observed." (PMID 41573652, 2025). "In a murine model, Ncom Gel markedly increased the percentage of CD80+ and CD86+ DCs in TDLNs, triggering an expansion of IFN-γ–producing CD8+ and CD4+ T cells and leading to a significant delay in tumor growth." (PMID 41294574, 2025). "High levels of CD4+ and CD8+ T cells, along with CD20+ B cell infiltration in the tumor mass, are associated with longer survival in NSCLC patients." (PMID 40136652, 2025). "Elevated IL-6 levels also inhibited the production of CD8+ and CD4+ T lymphocyte cells, creating a “cold” tumor microenvironment (TME) that was unfavorable for anti-PD-1 therapy." (PMID 40160826, 2025). "Analysis of immune cell composition and function within the tumor tissue revealed increased infiltration of CD4+ and CD8+ T cells and reduced immunosuppressive regulatory T cells (Treg) infiltration." (PMID 41445946, 2025). "In another study, high ratios of Tregs to CD4+ and CD8+ TILs were associated with poor prognostic markers, viz high histological grade and tumor recurrence." (PMID 41150099, 2025). "The tumor microenvironment composition including CD8 + T, CD4 + T, macrophages and tumor-associated fibroblasts relates with clinical outcomes in various cancers including gastric cancer." (PMID 41568291, 2025). "LIGHT fused to a vascular targeting peptide has been found to normalize tumor blood vessels, activate CD4+/CD8+ T cells, and triggers TLS formation in immunotherapy-resistant pancreatic adenocarcinoma." (PMID 40475770, 2025). "In contrast, activation markers CD39, CD69, and PD-1 were strongly upregulated on both CD8 and CD4 T cells in the tumor compared to the blood for all patients." (PMID 39918475, 2025). "They release immunosuppressive cytokines such as IL-10, IL-4, IL-13, IDO and TGF-β, reducing TNFα and INF-γ levels in effector CD4+ T cells, inhibiting APCs function, and downregulating tumor-specific cytotoxicity within the immune response." (PMID 41208963, 2025).
tumor (continued). "Prolonged recurrence-free survival, was associated with increased expression of T cell markers (CD4, CD8α, and PD-1) and elevated cleaved PARP levels in recurrent tumors, indicating enhanced anti-tumor immunity and apoptosis." (PMID 41208884, 2025). "CD4+ T cells are initiators of adaptive immunity, and their direct activation to target tumor antigens can launch a robust antitumor immune response in early epithelial cancers and precancerous lesions." (PMID 39744942, 2025). "Temsirolimus (TEM) activates autophagy to suppress tumor-derived sEV PD-L1 secretion and increase the number and activation of CD4+and CD8+T cells, inducing systemic anticancer immunity." (PMID 41246345, 2025). "This latter observation suggests that adding KLRG1 blockade to PD-1 blockade can further mobilize additional tumor-TCR-matching cytotoxic CD4+ T cells in the periphery to kill." (PMID 40299576, 2025). "The proportions of tumor-infiltrating CD4+ and CD8+ T cell subsets increased by 3.5-fold and 0.9-fold, respectively, consistent with the activation and proliferation observed in the spleen." (PMID 40978011, 2025). "There has been limited focus on TH1 cells, which are known as tumor suppressors within the CD4+ T cell population." (PMID 40611261, 2025). "For example, in chronic lymphocytic leukemia, elevated BTLA expression on CD4+ and CD8+ T cells is associated with impaired T cell-mediated anti-tumor responses, leading to immune exhaustion." (PMID 40739089, 2025). "CD4 T cells can play a pro-metastatic role by modulating pro-tumor macrophages via IL-4 signaling or by differentiating into immunosuppressive regulatory T cells that inhibit cytotoxic T cell proliferation." (PMID 40078995, 2025). "Tumor-bearing animals treated with PBS showed low CD4 and CD8 effector T cell counts in both the draining and non-draining lymph nodes, while TREG cell-depleted mice showed dramatic, but non-specific T cell expansion at both sites." (PMID 40478934, 2025). "In contrast, the low-risk group’s tumors were more enriched with hematopoietic stem cells (HSCs) and central memory CD4 T-cells (CD4+ Tcm), indicating a potentially more robust immune response against the tumor." (PMID 40362553, 2025). "In the current study we aimed to profile the distribution of neoantigen-specific CD4+ T cells (Th and Tregs) between the vaccination site, tdLNs and the tumor in relation to the tumor suppression." (PMID 40650228, 2025). "Other upregulated genes included NR3C1, NMB, and COTL1, which are coordinately expressed with PDCD1, CXCL13, and ENTPD1 by tumor infiltrating CD4+ T cells." (PMID 40956619, 2025). "Crosses of Rip1‐Tag5 mice to transgenic mice that either increased the abundance of anti‐Tag CD4+ T cells or rendered the tumor cells costimulatory (Rip‐B7‐1) dramatically enhanced the infiltration of premalignant lesions, but not of solid tumors." (PMID 40145271, 2025). "A deeper understanding of antitumor immunity has revealed critical components, such as the activation of tumor-cognate CD4+ T cells, which is required to drive effective antigen presentation and promote memory T-cell formation." (PMID 39704984, 2025). "Uptake of these EVs into T cells caused a downregulation of early T cell activation regulator CD69 expression, which leads to increased migration, immune synapse formation, and interaction of CD4+ T cells with tumor cells." (PMID 41551601, 2025). "We observe pronounced cDC1 recruitment in tumors throughout the body, a vigorous activation of CD8+ cytotoxic T cells and Th1‐type CD4+ T cells, and a reduction in the immunosuppressive cells such as M2‐polarized macrophages and Tregs in the tumor sites​." (PMID 41042114, 2025). "YBG induces apoptosis in polymorphonuclear MDSCs (PMN-MDSCs), which suppress anti-tumor response and facilitates the differentiation of M-MDSCs into mature antigen-presenting cells (APCs) capable of activating CD4+ ​​​​and CD8+ T cells." (PMID 41163402, 2025).
tumor (continued). "These platforms enhance the CD4+ T-cell support for cytotoxic T lymphocytes (CTLs), resulting in improved tumor cell destruction." (PMID 40860882, 2025). "Our data demonstrate that CCR9 shapes the tumor microenvironment, affecting the recruitment of effector CD4+, CD8+ and Treg cells subsets." (PMID 40305493, 2025). "CD4+ regulatory T (Treg) cells play a major role in limiting anti-tumor immunity, and Treg cell accumulation in tumors is often negatively associated with clinical outcomes and immunotherapeutic efficacy." (PMID 40468052, 2025). "The cycling T cell population (cluster 11) displayed a strong signature of proliferation-associated genes including Mki67 and Top2a and included CD8+ and CD4+ cells and represented about 18% of the entire T cell population in tumours." (PMID 40473819, 2025). "In contrast, basal proliferation of GZMK+CD4+ T cells in the periphery before treatment in patients with cancer suggests chronic activation stemming from the presence of tumor." (PMID 40299576, 2025). "The observation that Th1 and Th17 cells were higher in tumor-infiltrating cells during TC-1 growth implied that the E743–77-pulsed bm12 mBMDC vaccine induced allogeneic CD4+ T cell help." (PMID 40857404, 2025). "In these models, CIITA‐transfected/infected MHC‐II‐positive cells were found to activate CD4+ T‐cells, resulting in tumor rejection or growth retardation in mice with subcutaneous tumors." (PMID 39535369, 2025). "Among other downregulated genes notable is Fbln5, whose expression correlates significantly with the infiltration of various immune cells into the tumour, including CD4+ T cells, M0 and M2 macrophages." (PMID 40547518, 2025). "The CD4+ T cell ratio provides a more comprehensive view of the immune system’s ability to respond to and control tumor growth." (PMID 41179889, 2025). "CD8+ T cells predominate in the TME of GC due to their role in cytotoxic elimination of tumor cells, although CD4+ T cells are represented by large numbers of Treg cells." (PMID 40136652, 2025). "Mechanism: Vaccine containing nine HLA class I‐ and class II‐restricted peptides derived from both mutated and non‐mutated AML/LPC antigens that are tumour‐exclusive resulting in CD8+and Th1 CD4+T cell responses." (PMID 40619749, 2025). "Then, it is revealed that Plac1+ tumor cells recruit CD4+ T cells via CXCL11/CXCR3 and induce Treg differentiation via PVR/TIGIT, which in turn activates the tumorigenic signaling of Plac1+ tumor cells via LTA/LTBR and forms a reciprocal protumor loop." (PMID 40056047, 2025). "Utilizing the Pdx-Cre;KRASLSLG12D model, the authors detected enriched IL4, STAT6 and MYC level in these tumor lesion, which are dramatically infiltrated by CD4 + T cells, potentially contributing to pancreatic cancer initiation and progression." (PMID 39806421, 2025). "At present, some pre-clinical and clinical studies have confirmed that CD4-positive T cells have cytotoxicity that can directly kill cancer cells, but tumor killing is still attributed to CD8+T cell function." (PMID 40051494, 2025). "Trastuzumab upregulates major MHC-II molecules in the tumor microenvironment, increasing antigen availability for CD4+ T-cell activation." (PMID 40028325, 2025). "Recent studies have emphasized the critical role of immune cells, such as CD4+ T cells, CAFs, MDSCs, neutrophils and macrophages, in tumour immunotherapy, highlighting their undeniable importance in cancer treatment." (PMID 40275529, 2025). "Analysis of phosphorylated ERK and p38 in CD3+CD4+ lymphocytes revealed an increase in ERK phosphorylation following calcitriol treatment in aged 4T1 tumor-bearing mice." (PMID 40894304, 2025). "MHC-II–abundant APCs, including dendritic cells, macrophages, and B cells, play a central role in CD4+ T cell activation in the tumor microenvironment." (PMID 40608411, 2025). "Through TGF-β signaling, CD4+CD25− naïve T cells develop into T-regs that inhibit tumor-specific CD8+ T cell cytotoxicity and NK cell function." (PMID 40075726, 2025).
tumor (continued). "There is also a correlation between the CD8 + exhausted T cell population and the CD4 + Treg population, suggesting their collaboration in modulating tumor immune responses." (PMID 41035074, 2025). "More recently, however, accumulating evidence has demonstrated that CD4+ HTLs also possess direct cytotoxicity against tumor cells." (PMID 40723210, 2025). "The release of these mediators activates circulating dendritic cells, which take up dying tumor cells, migrate to lymph nodes, and present tumor antigens to naïve CD4+ T cells." (PMID 39941843, 2025). "CD4+ cells play a role in regulating tumor growth and metastasis, impacting cancer prognosis and treatment outcomes." (PMID 40362506, 2025). "According to the results of cell–cell communication analysis among C2, C5, and other clusters, terminal states of tumor-infiltrating CD4+ T cells were specifically enriched in the MIF signal pathway (MIF-CD74+CD44, MIF-CD74+CXCR4)." (PMID 41008548, 2025). "The TIMER algorithm was utilized to assess the infiltration levels of various immune cell subtypes in tumor samples, including B cells, CD4 + T cells, CD8 + T cells, macrophages, dendritic cells, and neutrophils." (PMID 40953006, 2025). "Although the response intensity is lower than that of CD8+ T cells, a sufficient number of CD4+ TILs can still exert significant tumor-killing effects." (PMID 40444078, 2025). "mIHC staining revealed that, compared to BTC patient samples with no response to camrelizumab combined with apatinib treatment, tumour tissues from responders exhibited significantly higher levels of CD4+ and CD8+ T cell infiltration." (PMID 40074697, 2025). "The infiltration rates of APCs and anti-tumor lymphocytes (such as CD4+ T cells and CD8+ T cells) were significantly higher in Subtype 4, which can be shown by the ssGSEA scores and the density of immune cells calculated by TIMER." (PMID 40141097, 2025). "Compared with the Chemo group, the Io+Chemo group exhibited greater infiltration by CD4+ cells in tumor, stroma and total (density: p= 0.022; stroma, p=0.006; total, p=0.010; percentage: tumor, p=0.020; H-score: tumor, p=0.010)." (PMID 39931056, 2025). "Similar to the effects observed in the OVA model, mHBsAg@NPs treatment resulted in an increase in tumor‐infiltrating CD3+/CD4+ and CD3+/CD8+ T cells, along with alteration in macrophage polarization." (PMID 39761175, 2025). "Although both these CD4 subsets show context-dependent roles in tumor immunity, Th2 T cells are broadly acknowledged as part of the immunosuppressive tumor immune environment, while Th17 cells thought to promote an anti-tumor immune response." (PMID 41210994, 2025). "The underlying mechanism involve increased infiltration of FOXP3+ and CD4+ Treg cells and CAFs within the tumor microenvironment." (PMID 41235229, 2025). "Depletion of methionine by tumor cells leads to up-regulation of PD-1 expression in CD4+ T cells, impairing their anti-tumor capacity." (PMID 40696413, 2025). "Tumor-infiltrating lymphocytes (TILs), particularly CD4+ and CD8+ T cells and their immunomodulatory cytokines, are critical components of adaptive immunity within the TME." (PMID 40787464, 2025). "Using the TIMER method, we found that SGO1 is significantly associated with the infiltration levels of various immune cells, including B cells, CD8+ T cells, CD4+ T cells, macrophages, neutrophils, and dendritic cells across different tumor types." (PMID 40861810, 2025). "Another approach is ligand-functionalization, in which nanoparticles are coupled with targeting ligands like aptamers, peptides, or antibodies to enable them to bind specifically to particular receptors on CD4+ T-cells or tumor cells." (PMID 40860882, 2025). "The capacity of CD4 T cells to reinforce tumor cytostasis parallels findings that Th1 CD4 T cells can induce senescence-like states in cancer cells through TNF-α and IFN-γ secretion." (PMID 40299790, 2025).